INS (insulin)
Diseases named in the same sentence as INS in open-access papers (continued):
Sharing a sentence is not in itself a finding about the gene and the disease.
Hypoglycemia (continued). "The CRR is the neuro-endocrine response to hypoglycemia that involves an increase in glucagon, corticosterone, and norepinephrine levels, and a reduction in insulin secretion." (PMID 34265067, 2021). "Insulin pump basal delivery can be reduced or suspended completely, which provides both a near-immediate response to hypoglycemia and the ability to address intermittent hypoglycemic trends with targeted titration." (PMID 34064129, 2021). "PLGS systems automatically suspend or decrease insulin delivery in response to impending hypoglycemia." (PMID 33535013, 2021). "Although evidence is limited, early studies have indicated a role for rtCGM in selected patients with non-insulin requiring T2D to improve glycemic control and/or reduce hypoglycemia." (PMID 33534631, 2021). "Since our data also demonstrated an increased plasma sNRP1 level 4-h post insulin-induced hypoglycaemia, it is highly likely that glycemic control-mediated improvement of severity in COVID-19 patients is associated with elevated sNRP1." (PMID 34248841, 2021). "Inappropriately high insulin and C-peptide concentrations were identified at the time of hypoglycemia." (PMID 34583764, 2021). "Many studies have described a fast occurring hyperglycemic peak after ingestion of carbohydrates, followed by a disproportionately exaggerated insulin response that lingers on longer than the hyperglycemia—leading to postprandial hypoglycemia." (PMID 33783679, 2021). "Insulin secretion is inhibited by hypoglycemia and decreased ATP production in β cells–this promotes KATP channel conductance, the cell membrane hyperpolarizes, and [Ca2+]i decreases." (PMID 35002748, 2021). "The relative frequency of patients with hypoglycemia during the hospitalization was 47.1% on insulin-based patients, 26.4% on secretagogue-based patients, 29.4% on non-secretagogue and 16.7% on insulin+secretagogue patients (p = 0.018)." (PMID 33402217, 2021). "The proportion of patients with hypoglycemia in the 12 months previous to admission was higher in patients on insulin-based therapy (66.1%) with statistically significant differences (p = 0.001)." (PMID 33402217, 2021). "While hypoglycemia and weight gain are well-known side effects of insulin therapy, the most important patient-related barriers to insulin therapy were related to its impact on the patient’s social life and misperceptions about the side effects of insulin." (PMID 34712538, 2021). "In sensor-pump integrated systems, predicted glucose levels can trigger actions by the insulin pump, like automatic insulin infusion suspension to mitigate impending hypoglycemia." (PMID 34064325, 2021). "Nevertheless, intensive glucose control can lead to hypoglycemia, frequently occurring during intensive anti-hyperglycemic treatment conducted with insulin or sulphonylureas/glinides." (PMID 33919723, 2021). "Prior to genetic testing, the proband (III3) was treated subcutaneously with 4 U short-acting insulin three times daily before meals and occasionally had hypoglycemia after conscious exercise at boarding school." (PMID 35002955, 2021). "Insulin-induced hypoglycemia enhances population activity of AVP neurons in the supraoptic nucleus (SON), driving glucagon secretion AAV-DIO-hM3Dq-mCherry was injected bilaterally into the SON of Avpires-Cre/+ mice." (PMID 34787082, 2021). "Hypoglycemia is the most common acute complication of diabetic patients receiving antidiabetic therapies, especially those receiving insulin therapies, and can be easily improved by adjusting the insulin dose or improving one’s lifestyle." (PMID 33827670, 2021). "It has been observed that individuals with T1D who increase their knowledge of nutrition and insulin adjustments to minimize PE-induced hypoglycemia also reduce their barrier to physical activity." (PMID 36994325, 2021).
Hypoglycemia (continued). "The FH is associated with the frequency of past hypoglycemic episodes and can promote compensatory behaviors, such as reducing insulin dosages to avoid hypoglycemia." (PMID 34342593, 2021). "After that, patients underwent an individual health education session about hypoglycemia and insulin pen." (PMID 34497858, 2021). "Among the 26 insulin-treated patients with a hypoglycemia-related adverse event, MACE occurred in 5 (19.2%)." (PMID 34158057, 2021). "This is a report of two patients who were first treated with insulin then replied to sulfonylurea, and because of recurrent hyper- and hypoglycemia, were successfully treated with meglitinide (repaglinide) and their follow-up for 9 and 10 years." (PMID 34696808, 2021). "In previous experimental studies of insulin-induced hypoglycemia, the effect of hypoglycemia on cardiac repolarization has been compared to cardiac repolarization during hyperinsulinemic euglycemia." (PMID 34085953, 2021). "It is important to know that, in severely burned patients, metformin is as effective as insulin in lowering the serum glucose levels and rarely produces hypoglycemia." (PMID 34502429, 2021). "Among the 22 patients who initiated insulin pump therapy because of disabling hypoglycemia, the proportion of patients reporting ≥1 episode at baseline decreased from 58.3% to 16.7%." (PMID 34077674, 2021). "Activation of mediobasal hypothalamic (MBH) AMPK is obligatory for optimum glucose counter-regulatory responses to insulin-induced hypoglycemia." (PMID 33490375, 2021). "Patients with IGF2-producing tumors have impaired glycogenolysis and gluconeogenesis with hypoglycemia and suppressed insulin secretion." (PMID 33849624, 2021). "Liver-selective glucokinase activators are very promising based on available data, as they reduce hypoglycemia while lowering peripheral glucose concentrations with lower insulin requirements." (PMID 34902055, 2021). "In recent years, hypoglycemia induced by exogenous insulin in diabetic patients has also shown symptoms similar to IAS." (PMID 33827670, 2021). "Active dose titration of basal insulin is important both for maintaining glycemic control and preventing hypoglycemia, and instructing patients in self-titration based on self-monitoring of FPG improves glycemic control." (PMID 34165382, 2021). "Third, a correction of the amount of insulin administered seems reasonable as increased rates of hypoglycaemia were reported." (PMID 34684559, 2021). "Out of 35 patients, 19 (54%) developed symptomatic hypoglycemia as a result of exaggerated insulin and C-peptide release in response to the mixed-meal." (PMID 33624213, 2021). "With the exception of one study dealing with spontaneous hypoglycemia, the majority of studies were based on experimental and intentional insulin-induced hypoglycemia." (PMID 34638984, 2021). "Potential harms include hypoglycemia due to insulins, and insulin secretagogues, and ketoacidosis due to SGLT2 inhibitors." (PMID 34434951, 2021). "With the avoidance of hypoglycaemia in mind, basal insulin is usually started at a low dose (0.1–0.2 units/kg/day), after which dose titration is guided by SMBG to achieve a fasting plasma glucose target, usually in the range 80–130 mg/dL." (PMID 34184589, 2021). "In the CGM group, 41.2% of youth reported sometimes experiencing hypoglycemia during PA, while this figure was 78.9%, 80.5% and 81.5% in insulin injection, insulin pump and blood glucose meters groups, respectively." (PMID 34557162, 2021). "After 9 weeks of insulin treatment, he began to have episodes of hypoglycemia, so we began a progressive reduction of his insulin dose." (PMID 33905625, 2021). "It was noticed that people often skip the evening dose of insulin because of fear of nocturnal hypoglycemia." (PMID 34826318, 2021). "GLP-1 RAs increase insulin secretion and inhibit the glucagon action in a glucose-dependent manner, making it less likely for hypoglycemia." (PMID 34209532, 2021).
Hypoglycemia (continued). "A prospective study showed that average blood glucose levels, maternal weight gain during pregnancy and the incidence of neonatal hypoglycemia in GDM patients treated with metformin were significantly lower than those in GDM patients treated with insulin." (PMID 33429755, 2021). "His most recent OGTT, performed at the age of 29 years, showed typical fasting hypoglycemia with hyperinsulinemia, followed by a decrease in glucose level with an excessively high insulin level 2–3 h after oral glucose load." (PMID 34680961, 2021). "In the relatively well-controlled population included in our study, automated insulin delivery system increased time spent in the target glucose range and reduced time spent in hypoglycemia, and the benefits were observed during the day and night." (PMID 33050728, 2021). "Surprisingly, although females exhibited a higher propensity for elevation of plasma insulin levels compared to males, fewer females developed hypoglycemia in response to fasting." (PMID 34862365, 2021). "Nevertheless, the tumors secrete high levels of insulin producing a hypoglycemia phenotype resembling INS." (PMID 34794032, 2021). "The most frequent adverse event was hypoglycemia in patients using dapagliflozin as an add-on to metformin plus insulin (n = 9/34), and there were two cases of major hypoglycemia." (PMID 33444492, 2021). "Here, the authors identified a glucose-responsive CRL4-COP1-ETV5 proteolytic axis that promotes insulin secretion, and is inhibited under hypoglycemia." (PMID 33911083, 2021). "Occasionally, she experienced hypoglycemia after conscious exercise or missed insulin injections while at boarding school." (PMID 35002955, 2021). "Management approaches:Diet and lifestyle advice.Medications: glibenclamide, metformin, glucagon, glucose injectable (hypoglycemia), insulin (soluble, intermediate, rapid human)." (PMID 33777712, 2021). "The DEPICT-2 Study demonstrated that dapagliflozin at 5 mg or 10 mg add-on insulin therapy was safe and well tolerated and exhibited a potential benefit in improving glycemic control and hypoglycemia in T1D." (PMID 34497852, 2021). "This is a scenario specific to hypoglycemia, since other stimuli, including administration of amino acids, insulin withdrawal, lipopolysaccharide exposure, exercise and even meals lead to profound glucagon responses." (PMID 34405569, 2021). "Hybrid closed loop systems (HCL, also called artificial pancreas) are insulin delivery systems that automate insulin delivery in addition to augmenting or suspending insulin for actual or predicted hypoglycemia." (PMID 37745178, 2021). "It has been shown that insulin-induced hypoglycemia has K+ channel blocking effects predominantly affecting the delayed rectifier repolarizing current (IK), which has a major role in the electrical activity of cardiac ventricular myocytes." (PMID 33898141, 2021). "Apart from achieving 2-h PPG within the guideline-defined range, another key consideration of the insulin-dose titration is safety, i.e., avoidance of hypoglycemia." (PMID 34071359, 2021). "The present paper contains data relating to the safety of CHADN as it relates to insulin‐induced hypoglycemia in diet‐induced glucose‐intolerant dogs." (PMID 33769710, 2021). "The hyperinsulinemic-hypoglycemic clamp, together with insulin-induced hypoglycemia and 2-DG induced glucoprivation, have been extensively used in Sprague-Dawley rats to investigate CRR, glucoprivic feeding and impaired awareness of hypoglycemia." (PMID 33868184, 2021). "Since most neurons in the VMH are glutamatergic, knocking out the glutamate transporter, VGLUT, selectively in SF1 neurons, resulted in an impaired CRR to insulin–induced hypoglycemia." (PMID 34265067, 2021). "During the period of insulin pump therapy, the average incidence of hypoglycemia was 0.04 ± 0.19 times/case." (PMID 33483468, 2021).
Hypoglycemia (continued). "In the immediate post-KT period, the combination of linagliptin plus basal bolus insulin regimen provided better glycemic control with lower insulin demands and less serious hypoglycemia than the basal bolus insulin regimen alone." (PMID 33808901, 2021). "However, the conventional therapeutic regimens but they do not always cannot accurately control the dose of insulin efficiently regulate insulin levels and thus, may cause serious hypoglycemia, resulting in poor compliance, with a resultant poor attainment of target glycemic level." (PMID 33705413, 2021). "Multiple studies in the United Kingdom have recognized several misperceptions about insulin use among patients, such as beliefs about insulin ineffectiveness, reduced quality of life, regimen complexity, hypoglycemia, weight gain, and needle injection pain." (PMID 34712538, 2021). "Insulin secretagogues can stimulate β-cell secretion of insulin, with weight gain and hypoglycemia as potential side effects." (PMID 33441946, 2021). "We adjusted the insulin dosage promptly according to the blood glucose levels to reduce the occurrence of hypoglycemia." (PMID 33660433, 2021). "On the contrary, carvedilol can cover the tachycardia, just like other adrenoreceptor blockers that serve as a warning indication for insulin-induced hypoglycemia in diabetic patients." (PMID 33532503, 2021). "There was unanimous agreement that preventing insulin-related hypoglycemia in hospitalized patients is an important priority, and 47% (48/102) either agreed or strongly agreed that preventing insulin-related hypoglycemia in the hospital is challenging." (PMID 34842544, 2021). "At baseline, patients were interviewed through a predefined, structural questionnaire to assess their knowledge about hypoglycemia and insulin pen use." (PMID 34497858, 2021). "For this purpose, experiments were carried out in chemically induced diabetic rats, which were subjected to repeated injections of insulin in order to induce recurrent bouts of hypoglycemia." (PMID 34948265, 2021). "The important finding from the present study is that an autonomous glucose control system can protect a subject from severe hypoglycemia (< 2.2 mmol/L) even when a very high intravenous insulin dose is given to perturb the system." (PMID 32006145, 2021). "In order to achieve and maintain glycaemic control, and prevent both hyper- and hypoglycaemia, current guidelines recommend frequent glucose monitoring in individuals using insulin and insulin secretagogues drugs." (PMID 33413148, 2021). "The intervention group needed a higher insulin dose and experienced more often hypoglycemia at the late pregnancy visit compared with the control group." (PMID 34976684, 2021). "We recommend examining patients for primary or secondary hypoadrenalism, IGF-1, C-peptide, ketones, sulfonylurea concentrations, and in some instances insulin in cases of unprovoked hypoglycemia in a diabetic." (PMID 34583764, 2021). "With the increasing use of insulin to treat type 2 DM in the elderly, the prevalence of hypoglycemia is likely to escalate." (PMID 33512324, 2021). "It is possible, at the end of the test, to perform a glucagon 1 mg infusion and if glucose increases to >25 mg/dL, this confirms the diagnosis of hypoglycemia secondary to endogen insulin secretion, as high insulin levels block glycogenolysis." (PMID 34199977, 2021). "Numerous clinical studies have shown that T1D patients who have an “insulinogenic reserve,” also referred to as being “C-peptide positive,” experience diminished glucose variability and enhanced plasma glucagon responses to insulin-induced hypoglycemia." (PMID 34003799, 2021). "Enrichment analysis of Gene Ontology (GO) biological processes showed that the regulation of insulin secretion, glucose homeostasis, apoptosis, nitric oxide biosynthesis, and cell signaling are significantly enriched for hypoglycemia." (PMID 34830301, 2021).
Hypoglycemia (continued). "This helps to prevent the development of hypoglycemia that results from excessive insulin administration beyond the required dosage." (PMID 36338772, 2021). "As anticipated, the higher strength of stock solution (1:3 vs 1:7 and 1:20 dilution), the longer duration of interval between insulin infusion and the higher frequency of hypoglycemia were observed." (PMID 34270619, 2021). "Most studies suggest that insulin pump therapy is more conducive to blood glucose control and can achieve lower HbA1c levels, less hypoglycemia (especially nocturnal hypoglycemia) and greater time in range so minimizing long-term complications." (PMID 34211433, 2021). "The advent of the artificial pancreas has brought many benefits to T1D patients, including improved TIR and less frequent hypoglycaemia, but it has yet to eliminate the need for insulin injection and blood glucose monitoring." (PMID 34202521, 2021). "Numerous models of liver transplant showed that the counterregulatory response to insulin‐induced hypoglycemia or exercise (swimming and running) is normal." (PMID 33769710, 2021). "Along with our data, it has been proposed that it is possible to predict hypoglycemia events and insulin doses delivered to DM patients." (PMID 33707491, 2021). "Hypoglycemia is the main side effect of exogenous insulin use, and in addition to acute changes in mental status, severe hypoglycemia can cause cognitive impairment, falls leading to fractures, and cardiac arrhythmias, resulting in sudden death." (PMID 34917025, 2021). "This feasibility study has identified practical and technical aspects important for a larger observational study using CGM to identify hypoglycemia in home-dwelling older individuals receiving home care using insulin or other glucose-lowering drugs." (PMID 33407924, 2021). "The ACP (American College of Physicians) recommends routine SMBG for patients: on insulin; with evidence of hypoglycemic episodes; or, taking drugs likely to increase hypoglycemia while driving or operating machinery." (PMID 34758807, 2021). "The 4-T study demonstrated that a single injection of basal insulin is as effective as a prandial and a premixed insulin in reducing HbA1c, but with less hypoglycemia and weight gain." (PMID 34063071, 2021). "Modern medical treatment of T2DM mainly focuses on the control of blood sugar by oral hypoglycemic drugs and injection of insulin, whereas improper use of insulin can lead to hypoglycemia." (PMID 34579756, 2021). "The diagnosis of INS is reached through the combination of concomitant hyperinsulinemia and hypoglycemia with the exclusion of alternative diagnoses such as exogenous insulin administration." (PMID 34794032, 2021). "His most recent 4-h OGTT, performed at the age of 57 years, showed typical fasting hypoglycemia with hyperinsulinemia, followed by a decrease in glucose level with an excessively high insulin level 2–3 h after oral glucose load." (PMID 34680961, 2021). "Congenital hyperinsulinism (CHI) is characterized by dysregulated insulin secretion, resulting in severe hypoglycemia." (PMID 34682101, 2021). "CRH stimulation test that has lower standardization and availability and insulin-induced hypoglycemia test which is the gold standard test for AI diagnosis., However, complications have limited insulin-induced hypoglycemia test's applicability." (PMID 34557164, 2021). "Compared with other antidepressants, MAOI often increases the sensitivity of patients to insulin and is prone to hypoglycemia, weight gain, and different adverse reactions." (PMID 34408704, 2021). "Subjects underwent insulin-induced hypoglycemia with blood sampling at baseline, hypoglycemia and post-hypoglycemia; SOMAscan proteomic analysis of complement pathway-related proteins, cytokines and inflammatory proteins was undertaken." (PMID 36643727, 2021). "Providing instructions how to adjust insulin can reduce the frequency of hypoglycaemia in T2D patients." (PMID 34126938, 2021).